MFN1 (mitofusin 1)
Diseases named in the same sentence as MFN1 in open-access papers (continued):
Sharing a sentence is not in itself a finding about the gene and the disease.
vascular disorder (1 paper, 2020). A general term used to describe any disease affecting blood vessels]. "Targeting the Klf5-eIF5a/Mfn1 regulatory pathway provides a potential therapeutic strategy for age-related vascular disorders." (PMID 32817651, 2020).
MFN1 also shares sentences with these, for which no sentence is quoted: acute myocardial infarction (5 papers); cardiovascular diseases (4); depression (4); diabetic cardiomyopathy (4); Anxiety (2); glioblastoma (2); hypertrophy (2); mitochondrial disease (2); neurological disease (2); pulmonary arterial hypertension (2); amyotrophic lateral sclerosis (1); aneurysm (1); bacterial infection (1); breast tumors (1); cardiac arrest (1); centronuclear myopathy 1 (1); chronic lymphocytic leukemia (1); co-infection (1); colorectal cancer (1); COVID-19 (1); Crohn disease (1); diabetic nephropathy (1); diabetic retinopathy (1); endometrial cancer (1); endothelial dysfunction (1); gout (1); head and neck squamous cell carcinoma (1); hematological malignancies (1); Hyperammonemia (1); Hypertension (1).
A further 25 diseases each share a sentence with MFN1 in 1 paper.